GAS1 (growth arrest specific 1)
Diseases named in the same sentence as GAS1 in open-access papers (continued):
Sharing a sentence is not in itself a finding about the gene and the disease.
tumor (continued). "A tube formation assay indicated that GAS1 inhibited tumor angiogenesis in T24 and EJ cells." (PMID 33499877, 2021). "Moreover, SLUG also functioned to diminish the pro-apoptosis role of GAS1, thus harnessing the previously regarded tumor suppressor gene to serve as a tumor promoting gene." (PMID 32104513, 2020). "Comparison of the laBCC tumours before systemic treatment with localised BCC tumours yielded a significant differential expression of three genes of the Hh pathway: GAS1, GLI similar 2 (GLIS2), and protein kinase CAMP-activated catalytic subunit gamma (PRKACG) (P < 0.05)." (PMID 31988301, 2020). "This could lay the ground for future research of the role of GAS1 in the Hh pathway in general and in the resistance of the tumour to biologic treatment with Vismodegib." (PMID 31988301, 2020). "In our study, the higher pretreatment GAS1 levels in the partially responding laBCCs may suggest that these tumours were more aggressive and therefore able to spread even with these GAS1 levels, making them relatively resistant to the systemic treatment." (PMID 31988301, 2020). "The overexpression of GAS1 in laBCC may correspond to its higher level of expression in the partially treatment-responsive than in the completely responsive tumours." (PMID 31988301, 2020). "This emphasizes the importance of finding innate immune system stimulators since not only will the tumor microenvironment be rendered more hostile to tumor growth, but important downstream pathways such as Gas1 may be activated that can help combat the tumor." (PMID 30327548, 2018). "The knowledge of how Gas1 is regulated in quiescence may contribute to understand the deregulation occurring in neoplastic diseases." (PMID 21858068, 2011). "The amount of gas-1 mRNA in the tumours was in general higher than in normal tissues." (PMID 1379061, 1992). "The higher steady state level of gas-1 mRNA in spite of a shorter mRNA half life suggests that in CB-20 cells the gas-1 gene is transcribed faster than in CA-2 cells indicating that transcriptional regulation is the major determinant of gas-1 gene expression in tumour cells." (PMID 1379061, 1992). "Intriguingly, GAS1, which has been reported to play a role in growth suppression, blocks entry into the S phase, prevents the cycling of normal and transformed cells, and functions as a putative tumor suppressor, whereas it had the opposite effect in our study." (PMID 39600695, 2024). "Further analysis to identify which of the genes could have predictive value in terms of tumour response to systemic treatment yielded only one, GAS1, which had a significantly higher level of expression in tumours with a partial response than in those with a complete response." (PMID 31988301, 2020). "Gas1 negatively regulates the AMPK/mTOR/p70S6K signaling axis and modulates the proliferation, metastasis and abnormal metabolism of malignant tumor cells." (PMID 36843929, 2023). "GAS1 reduction reversed the inhibitory effects of ATOH1 overexpression on heterologous tumor growth and tumor initiation." (PMID 37824217, 2023). "On the contrary, GAS1 and GAS3 displayed high tumor targeting and lower background levels after labeling with either Ga-67, In-111, or Lu-177." (PMID 35336041, 2022). "Consistent with the previous conclusion that the EMT signature is a potential factor for tumor invasion and metastasis, the genes related to the EMT signature, including MGP, GAS1, and JUN, were found in Scissor+ cells of metastatic HGSOCs lesions." (PMID 35935940, 2022). "Recent studies proved that some oncogenes and tumour suppressors, such as PTEN, HIF-1a, Myc, KLF4, FOXM1, and Gas1 regulate glycolysis in cancer cells." (PMID 29463261, 2018). "GAS1 is a protein coding gene that, similar to GAS5, exerts its tumor suppressor actions through arresting the cell cycle and stimulating apoptosis." (PMID 30289954, 2018).
tumor (continued). "Of particular interest is GAS1, an apoptosis inducer, which is inactivated in a wide range of different cancers, as well as RECK, a tumor and metastasis suppressor." (PMID 25886003, 2015). "Besides, GAS1 was identified as a novel NOTCH4 target gene in this work to contribute to cancer stemness, although GAS1 has long been regarded as a tumor suppressor gene due to its canonical role in inhibiting cell proliferation." (PMID 32104513, 2020). "Subsequently, GAS1 was mapped to human chromosome 9q21.3-22.1 and established as a negative cell cycle regulator and tumor suppressor." (PMID 27811357, 2016). "In five chemically-induced mouse tumours grown in vivo the amounts of gas-1 mRNA were largely different but not related to the proliferating activity (evaluated by both H3 histone expression and 3H-thymidine incorporation into DNA)." (PMID 1379061, 1992).
cancer (38 papers, 2008 to 2025). A tumor composed of atypical neoplastic, often pleomorphic cells that invade other tissues. "Taken together, the results demonstrate that ATOH1 loss promotes cancer stemness through the ATOH1/GAS1/RET/AKT/mTOR signaling pathway in GAC, thus providing a potential therapeutic strategy for AKT/mTOR inhibitors in GAC patients with ATOH1 deficiency." (PMID 37824217, 2023). "Further mutations in cancer-related genes included Nav3 (V1129L), Cenpf (D1327E), Muc5ac (A429P), Mpp7 (Q158R), Gas1 (G326R), Maged2 (A473S), Dusp1 (C24R), Ros1 (W1875C), Polr2a (M1102I), Rragd (L385P), and Hoxa9 (insertion of “G” in UTR)." (PMID 32793490, 2020). "GAS1, a known cell growth suppressor linked to the outer membrane via glycosylphosphatidylinositol, was determined as a key regulator of tumorigenesis and cancer progression." (PMID 41214390, 2025). "Epigenetic inactivation of tumor suppressor genes EYA4 and GAS1 are associated with progression of various cancer types, but silencing of these genes might associate with progression of pituitary prolactinoma." (PMID 33709028, 2021). "GAS1 plays a major role in embryonic development and human diseases and involved stem cell renewal and cancer growth." (PMID 32155950, 2020). "For cancer related genes, Nav3, Cenpf, Muc5Ac, Mpp7, Gas1, MageD2, Dusp1, Ros, Polr2a, Rragd, Ros1, and Hoxa9 are mutated." (PMID 32793490, 2020). "Gas1 is a pleiotropic protein that can inhibit cell growth and induce apoptosis in cancer cells and actively participates in mammalian embryonic development." (PMID 27391369, 2016). "It has been suggested that GAS1 mediates hedgehog signaling, one of the pathways involved in cancer development and metastasis as well as in the maintenance of the cancer stem cell phenotype." (PMID 26161998, 2015). "GAS1 is highly expressed in quiescent mammalian cells and its over-expression in normal and some cancer cell lines was reported to inhibit G0/G1 transition." (PMID 24341352, 2013). "Component 2 (cytokine-linked hematopoietic signaling in cancer pathways) comprised proteins involved in chemotaxis, extracellular matrix regulation, and tissue remodeling, including Eotaxin, RANTES, Decorin, FLT3 ligand, Galectin-1, and Gas1." (PMID 41282065, 2025). "Interestingly, GAS1 impeded colorectal tumorigenesis through WNT signaling, influencing CD143+ cancer-associated fibroblasts." (PMID 39494300, 2024). "Furthermore, disruption of Gas1 and Boc has highlighted their importance in human diseases, including cancer." (PMID 27811357, 2016). "Oppositely, the inverse correlation between the two could also suggest that miR-34a inhibits GAS5, making its under-expression a cause of cancer rather than a result, as in the case of the miR-34a-GAS1 interaction." (PMID 30289954, 2018). "GAS1 acts as a novel biomarker and inhibits proliferation, angiogenesis, EMT and glycolysis in human cancers." (PMID 33499877, 2021). "We expanded this observation to more cell lines by analyzing the RNA-seq data retrieved from Cancer Cell Line Encyclopedia (CCLE), demonstrating that SLUG and GAS1 were positively correlated with NOTCH4 in TNBC cell lines." (PMID 32104513, 2020). "Our results show new functions for CGGBP1 in cell cycle, in regulation of expression of CDKN1A and GAS1, and provide insights into how CGGBP1 depletion overrides the redundancies of checkpoint escape mechanisms present in different cancer cells." (PMID 21733196, 2011). "Fifteen of the proteins we identify associated with cancer risk, including SFTPB and GAS1, did not appear to be under active current investigation as a drug target." (PMID 38684708, 2024). "Interestingly, GAS1 has been reported to serve as a novel biomarker and inhibit proliferation, angiogenesis, EMT and glycolysis in human cancers." (PMID 33499877, 2021).
cancer (continued). "In this article, our main objective was to find out the effects of those cross talking molecules, such as RAS, TWIST, ERK12, NOTCH1 or the loss of functions of few tumor suppressor proteins such as SUFU, GAS1, SUFU, NUMB, SNO in the three types of cancer scenarios discussed earlier." (PMID 23935937, 2013). "The livers of the animals transfected with Gas1, while developing DEN-induced HCC (group G) showed more normalized areas, although hyperplastic, adenomatous, and some carcinoma areas were still visible." (PMID 26161998, 2015).
infection (13 papers, 2013 to 2025). The state of being infected such as from the introduction of a foreign agent such as serum, vaccine, antigenic substance or organism. "Consistent with the previous observation, we confirmed that GAS1 showed peak expression at 8 hpi, which was associated with an appressorium-mediated infection as module 2 genes." (PMID 37233285, 2023). "To confirm the effect of pre-treatment on the formation of infection cushion, we observed the expression of the Appressorial Penetration-associated gene (GAS1) in the pathogen." (PMID 35082805, 2021). "We reasoned that these candidate effector genes might be involved in the initial step of infection since known pathogenicity genes Gas1 and Gas 2 (encoding putative secreted proteins) were included in cluster I." (PMID 31560822, 2019). "Gas1 is an ortholog of Egh16/Egh16H family members, which are highly expressed in the infection stage and are involved in pathogenesis." (PMID 34224331, 2021). "This low expression of the GAS1 gene directly correlated with a much lower number of infection cushions in MeJA and SA-primed plants than control at all time points." (PMID 35082805, 2021). "These records further corroborate the role the GAS1 gene plays in the infection and virulence process." (PMID 34947055, 2021). "The GAS1 protein in Magnaporthe grisea, which contains an Egh16-like domain, has been shown to participate in appressorial penetration and lesion formation, both of which are early events during infection." (PMID 39239924, 2024). "Surprisingly, we also observed that several genes related to inflammatory process (il1b, il10, tgfb) were repressed after 35 h of infection with the low dose of Gas1, and could be explained by a modified dynamic of gene expression over time." (PMID 34295335, 2021). "Finally, it is possible that their structure influences their absorption in the intestine and the binding to the receptor, and this should be further investigated to understand why Gas1 is such more efficient to protect fish against pathogen infection." (PMID 34295335, 2021). "Similarly, expression of several genes in the canonical IFN signaling pathway, including Ifng, Jak2, Stat1, Stat2, Socs1, Irf1, Irf9, Tap1, Ifitm1, Psmb8, Ifi35, Gas1 and Fit3 were up-regulated during infection by the mutant strain." (PMID 25201772, 2014). "In turn, for the GAS1 serum sample, which was isolated from a patient with an ongoing infection caused by S. pyogenes, no bands of the size 45 or 47 kDa were present, which may indicate high species specificity of these proteins." (PMID 35391726, 2022). "Inactivation of four of them (ant-1.1, atp-4, spg-7, and ucr-1) abrogated nlp-29 gene expression after infection to the same degree as the positive control, dcar-1, while knocking down gas-1 did not have a statistically significant effect." (PMID 27129311, 2016).
Bacterial Infections (1 paper, 2021). "After the bacterial infection, only lysozyme and mpo genes were affected by the type of β-glucan with an increase of their expression with Gas1 in comparison with MG diet (p < 0.05)." (PMID 34295335, 2021). "Therefore, the higher mpo gene expression could have induced a higher production of the enzyme leading to a higher oxidant capacity to deal with the bacterial infection in fish fed Gas1 diet." (PMID 34295335, 2021).
kidney disease (1 paper, 2022). "As a class of small single-stranded noncoding RNA, miR-34a is involved in the pathological process of various diseases such as dietetic kidney disease by regulating the function of target genes such as Egr1, GAS1, and Sirt1/HIF-1α." (PMID 36345369, 2022).
GAS1 also shares sentences with these, for which no sentence is quoted: acute liver failure (1 paper); brain injuries (1); clear cell renal cell carcinoma (1); colorectal adenocarcinoma (1); diabetic nephropathy (1); endometriosis (1); Endometrium (1); fibrosarcoma (1); gastric adenocarcinoma (1); Glomerular sclerosis (1); Hyperglycemia (1); keloid (1); leukemia (1); lung adenocarcinoma (1); measles (1); myeloma (1); non-small cell lung carcinoma (1); peripheral artery disease (1); pertussis (1); sarcoma (1); type 1 diabetes (1).